TBC1D2 (TBC1 domain family member 2)
Description:
Acts as a GTPase-activating protein for RAB7A. Signal effector acting as a linker between RAC1 and RAB7A, leading to RAB7A inactivation and subsequent inhibition of cadherin degradation and reduced cell-cell adhesion.
Synonyms: PARIS-1; PARIS1; TBC1D2A; Armus
Tractability: Antibody: its Gene Ontology location is reachable by antibodies, with high confidence; the Human Protein Atlas places it where antibodies can reach. PROTAC: ubiquitination databases record sites on it; its protein half-life has been measured.
Gene: Protein-coding gene on chromosome 9 (98,199,011 to 98,255,649, reverse strand). Ensembl gene ENSG00000095383.
Subcellular location: Cytoplasm; Cytoplasmic vesicle; Cell junction
Subcellular location (Human Protein Atlas): Cytosol; Nucleoplasm; Plasma membrane
Pathways (Reactome):
Vesicle-mediated transport: TBC/RABGAPs
Gene Ontology:
Molecular function: cadherin binding; GTPase activator activity; protein binding
Biological process: positive regulation of GTPase activity; regulation of cilium assembly
Cellular component: cell junction; cytoplasmic vesicle; cytosol; cytoplasm; plasma membrane; anchoring junction
Genetic constraint (gnomAD): Loss-of-function variants: 58 observed, 90.66 expected, observed/expected ratio (o/e) 0.64, 90% interval 0.52 to 0.8. The upper end of that interval is the gene's LOEUF score, 0.8, which puts it in group 3 of 6, group 1 being the genes least tolerant of losing a copy. Missense variants: 1,080 observed, 1,229.6 expected, observed/expected ratio (o/e) 0.88, 90% interval 0.83 to 0.92. Synonymous variants: 482 observed, 519.73 expected, observed/expected ratio (o/e) 0.93, 90% interval 0.86 to 1.
Homologues: Orthologues: chimpanzee TBC1D2 (99% identical), macaque TBC1D2 (96% identical), dog TBC1D2 (85% identical), rat Tbc1d2 (82% identical), mouse Tbc1d2 (82% identical), guinea pig TBC1D2 (81% identical), pig TBC1D2 (80% identical), rabbit TBC1D2 (79% identical), zebrafish tbc1d2 (45% identical). Paralogues in human: TBC1D2B (39% identical), TBC1D1 (18% identical), TBC1D4 (16% identical), TBC1D10B (15% identical), TBC1D9B (15% identical), TBC1D9 (15% identical), RABGAP1 (14% identical), TBC1D8B (14% identical), TBC1D8 (14% identical), RABGAP1L (14% identical), TBCK (13% identical), TBC1D10C (12% identical), and 33 more.
Diseases named in the same sentence as TBC1D2 in open-access papers:
TBC1D2 is named in the same sentence as 19 diseases in open-access papers, as found by Europe PMC text mining. Sharing a sentence is not in itself a finding about the gene and the disease. The quoted sentences say what the papers report.
ovarian carcinoma (3 papers, 2022 to 2025). A malignant neoplasm originating from the surface ovarian epithelium. "Our study revealed that TBC1D2 is overexpressed in ovarian cancer and is associated with a poor prognosis." (PMID 35574392, 2022). "In summary, our findings demonstrate that TBC1D2 serves as an oncogene in ovarian cancer and high expression level of TBC1D2 is associated with poor prognosis." (PMID 35574392, 2022). "To investigate the specific mechanism by which TBC1D2 promotes ovarian cancer progression, we studied at first if TBC1D2 modulates OC cell migration and invasion through regulating RAC1 and IQGAP1." (PMID 35574392, 2022). "This study investigated the expression profile of TBC1D2 in ovarian cancer and its clinical implications." (PMID 35574392, 2022). "To explore the role of TBC1D2 in ovarian cancer, we analyzed the mRNA expression in tumors from 426 OC samples and relevant normal tissues from 88 samples according to GEPIA 2 website." (PMID 35574392, 2022).
cervical cancer (2 papers, 2022 to 2025). A primary or metastatic malignant neoplasm involving the cervix. "Although miR-17-5p has been previously reported to regulate endocytic trafficking by targeting TBC1D2 in cervical cancer, no significant changes were found between OC and peritumor tissues in our study." (PMID 35574392, 2022).
breast carcinoma (1 paper, 2023). "In breast cancer cells, persistent Rac1 activity enhanced escape of β4 integrin from lysosomal degradation depending on actin-related protein 2/3 and TBC1D2." (PMID 36639648, 2023).
intracranial aneurysm (1 paper, 2022). "All genes except SYCP1 were expressed in intracranial aneurysm and control cerebral artery tissue, while FMNL2 and TBC1D2 showed high gene expression in these tissues, further prioritizing these genes." (PMID 35228681, 2022).
lung carcinoma (1 paper, 2022). "TBC1D2 is a GTPase activating protein of Rab7, and TBC1D2 contributes to the survival and proliferation of nasopharyngeal carcinoma cells and the metastasis of lung cancer cells." (PMID 36437242, 2022).
melanoma (1 paper, 2022). A malignant, usually aggressive tumor composed of atypical, neoplastic melanocytes. "The relationship between TBC1D2 and melanoma has not been reported." (PMID 36437242, 2022).
psychosis (1 paper, 2016). "Of these validated MAP biomarkers, four were previously reportedto predict psychosis in an independent human blood transcriptomeinvestigation (FBP1, ZNF821, TBC1D2 andSIN3A), one of which was previously labelled a genetic variantfor SCZ risk (FBP1)." (PMID 27163203, 2016).
renal tumors (1 paper, 2017). "Specifically, the transcript expressions of AKR1C1, S100A2, PLAU, SLC3A2, TBC1D2, and WIZ were decreased, while expressions of TGM2, SLC7A5, and NMI were increased in renal tumors when compared with non-tumorous control samples." (PMID 29272308, 2017).
Salmonella Infections (1 paper, 2021). Infections with bacteria of the genus SALMONELLA. "Many of these genes (e.g. Lhfpl2, Bhlhe41, Hyal1, and Tbc1d2) have previously been reported as differentially expressed in M1 vs. M2 macrophages and their downregulation likely represents M1 polarization that occurs following Salmonella infection." (PMID 34305890, 2021).
tumor (6 papers, 2019 to 2025). "However, PIK3R3 expression was higher in tumor specimens having somatic mutations in TBC1D2." (PMID 35761259, 2022). "On the contrary, TBC1D2 overexpression in A2780 cells enhanced the ability of tumor metastasis in vivo." (PMID 35574392, 2022). "Meanwhile, TBC1D2 promoted OC cell proliferation, migration, and invasion in vitro and facilitated tumor growth and metastasis in vivo." (PMID 35574392, 2022). "Our findings indicated that TBC1D2 is overexpressed in OC and contributes to tumor metastasis via E-cadherin degradation." (PMID 35574392, 2022). "Much more TBC1D2 mRNA expression was found in tumor tissues compared with that in normal tissues." (PMID 35574392, 2022). "In addition, to define the specific relationship between TBC1D2 expression and the infiltrative level of different subsets of immune cells in OC microenvironment, Tumor Immune Estimation Resource (TIMER) was employed." (PMID 35574392, 2022). "In addition, originally being an immunogenic tumour antigen, TBC1D2 may play a role in regulating cancer cell differentiation and growth." (PMID 35574392, 2022). "The levels of eight genes (SPI1, RNASE6, C1QB, C1QC, CSF1R, C1QA, TBC1D2, and ATP6V0E1) expression were higher in tumor samples from UALCAN." (PMID 32038997, 2019).
cancer (5 papers, 2019 to 2025). A tumor composed of atypical neoplastic, often pleomorphic cells that invade other tissues. "However, the clinical significance and potential roles of TBC1D2 were rarely explored in cancers." (PMID 35574392, 2022). "The expression levels of TBC1D2 and ATP6V0E1 were increased in both ESCC and HNSCC tissues, and they are closely related to the overall survival of ESCC and HNSCC, which means that TBC1D2 and ATP6V0E1 could be common therapeutic targets for both cancers." (PMID 32038997, 2019).
TBC1D2 also shares sentences with these, for which no sentence is quoted: anxiety disorder (1 paper); autism (1); nasopharyngeal carcinoma (1); neurodegenerative disease (1); ovarian tumors (1); skin cutaneous melanoma (1); thyroid cancer (1); Tumor Metastasis (1).